CTLA4 (cytotoxic T-lymphocyte associated protein 4)
Diseases named in the same sentence as CTLA4 in open-access papers (continued):
Sharing a sentence is not in itself a finding about the gene and the disease.
tumor (continued). "In murine models it was verified that immunotoxins can induce anti-tumor immunity and can be used locally to prime tumors to an immune attack elicited by anti-CTLA-4." (PMID 30621280, 2019). "After ibrutinib treatment, T cells show decreased expression of the inhibitory receptors PD-1 and CTLA-4, Treg numbers are decreased, and anti-tumor TH1 responses are increased." (PMID 31484424, 2019). "Through antibody-mediated inhibitory interaction at certain immune checkpoint receptors, especially cytotoxic T-lymphocyte-associated antigen 4 (CTLA-4), programmed cell death protein (PD-1) and its ligand (PD-L1) anti-tumor immune responses are enhanced." (PMID 31653079, 2019). "For instance, CTLA-4 modulates immune response primarily in draining lymph nodes, whereas the primary site of action of PD-1 and its ligands (PD-L1/PD-L2) is in the tumor microenvironment (TME)." (PMID 31412566, 2019). "Anti-CTLA-4 treatment reduces the activation threshold of T cells and magnifies the tumor-specific immune response." (PMID 30935414, 2019). "Anti‐CTLA‐4 and anti‐PD‐1 antibody are both immune checkpoint inhibitors that activate tumor‐specific CD8+ T‐cell responses." (PMID 30923782, 2019). "PD1 and CTLA4 are dynamically expressed on different T cell subsets that can either disrupt or sustain tumor growth." (PMID 31590386, 2019). "TNBC tumour cells use the PD-1/PD-L1 and CTLA4 immune pathways to avoid immune surveillance and proliferate but these monoclonal antibodies facilitate an effective immune-mediated and anti-tumour response." (PMID 31448088, 2019). "They promote tumor growth by iCP expression (CTLA-4, PD-1 and others) as well as production of IL-10 and TGF-β." (PMID 31555274, 2019). "Treatment with anti-CTLA-4 antibody decreases tumor burden, Treg presence, and Treg to CD4+ and CD8+ ratios." (PMID 31681327, 2019). "More importantly, CTLA-4 has been reported to be one of the selectively expressed proteins on tumor-infiltrating T cells in HNSCC." (PMID 31881947, 2019). "For instance, it inversely correlates with the probability of achieving a tumor response in metastatic melanoma patients treated with anti- Cytotoxic T-Lymphocyte Antigen 4 (CTLA4) mAbs." (PMID 30769874, 2019). "In primary non metastatic patients, only a high tumor grade (G3, HR = 4.4, p = 0.001), CTLA-4 expression (HR = 2.5, p = 0.005), and the combination of PD-1 and CTLA-4 expression (HR = 16.3, p < 0.001) are significantly associated with a worse CSS." (PMID 31137694, 2019). "CTLA4, MZB1, NIP7, and BUB1B in ADC, as well as GNG11 and CCNB2 in SCC, are novel top hub genes in modules associated with tumour size, SUVmax, and recurrence-free survival." (PMID 31877723, 2019). "CTLA-4 is a checkpoint inhibitor, which stops naive T-cell activation in the initial stage and thus inhibits the anti-tumor immune response." (PMID 30884772, 2019). "In fact, several preclinical murine studies have shown that combined anti-PD-1/CTLA-4 regimes decrease tumor progression and prolong survival." (PMID 30917934, 2019). "Some of these molecules (PD-1, CTLA4) are important targets for immunotherapy to promote anti-tumor immunity." (PMID 31624246, 2019). "Blockade of CTLA-4 has been shown to induce T cell activation and anti-tumor immunity in preclinical models." (PMID 30930892, 2019). "For example, combination immunotherapy in which the vaccine is administered with the anti-CTLA-4 mAb has been demonstrated to significantly enhance anti-tumor immune responses compared to administration of either the vaccine or mAb alone." (PMID 31134084, 2019). "Immune Checkpoint Inhibitors (ICPIs) are promising new drugs in treatment of advanced tumours targeting cytotoxic T-lymphocyte antigen-4 (CTLA-4) and programmed cell death protein-1 (PD1) or its ligand (PDL-1)." (PMID 31604452, 2019). "Vorinostat alone, the immunotherapy combination (anti-PD-1 + anti-CTLA-4) and the three-drug combination reduced tumor burden by 12.5%, 34%, and 88.5%, respectively." (PMID 31067680, 2019).
tumor (continued). "While the use of nivolumab and ipilimumab (humanized anti-CTLA-4 IgG1 mAb) in the post allo-SCT relapse setting in hematologic malignancies has demonstrated potent anti-tumor effects, significant immune-related adverse events (irAE) have also been reported." (PMID 31186046, 2019). "As for anti-PD-1 antibodies, anti-CTLA4 antibodies were designed to block inhibitory signals received from T cells by the tumor microenvironment, allowing anti-tumor immune responses to be reactivated." (PMID 31614774, 2019). "This immune phenomenon has been recently reported to limit the anti-tumor efficacy of the anti-PD-1/anti-CTLA-4 combined treatment in a low tumor burden setting characterized by tumor infiltration with partially exhausted T lymphocytes." (PMID 31309173, 2019). "A PEGylated liposome with an encapsulated anti-CTLA-4 antibody can effectively deliver CTLA-4 to the tumor site and enhance the immune response." (PMID 31371782, 2019). "While anti-CTLA-4 monotherapy at the selected dose and regimen still shows only minimal tumour response, anti-PD-L1 monotherapy and combination therapy suggest that the stronger the neoantigen is, the better the tumour response is." (PMID 31218069, 2019). "Another co-inhibitory molecule targeted in tumor immunotherapy, besides PD-1, is cytotoxic T-Lymphocyte protein 4 (CTLA-4)." (PMID 31766386, 2019). "While for anti-CTLA-4 Abs, hIgG1 isotype is critical since depletion of CTLA-4+ Treg cells instead of blocking CTLA-4-mediated suppressive signal is dominant mechanism for anti-tumor effect." (PMID 31105267, 2019). "Monoclonal antibodies that target PD-1 and CTLA-4 promote activation and expansion of T cells by blocking these immune checkpoints and have demonstrated efficacy in a wide range of tumor types." (PMID 31889898, 2019). "In a preclinical study, adoptive transfer of B. fragilis-reactive CD4+ T cells conferred enhanced tumor control and restored anti-CTLA-4 efficacy in GF mice." (PMID 30995949, 2019). "Application of this system to plasma of patients with several types of tumours demonstrated that soluble PD-1, PD-L1, and CTLA-4 levels were increased compared to those of healthy controls and varied among tumour types." (PMID 31300681, 2019). "The mAb-mediated clearance of soluble MIC has shown promising synergy with the IL-15 agonist ALT-803 mAb and enhanced anti-tumour responses with anti-CTLA4 checkpoint blockade therapy in clinically relevant models." (PMID 30626155, 2019). "The IL-15/IL15 receptor α complex showed synergy and improved anti-tumor effects when combined with anti-CTLA4 and anti-PD-L1 ICI." (PMID 31614774, 2019). "The main immunotherapy targets are programmable death protein 1 (PD-1) and cytotoxic T-lymphocyte-associated protein 4 (CTLA-4), checkpoint molecules that regulate the function of tumor-specific T-cells." (PMID 31366129, 2019). "Combination of anti- PD1 or anti- CTLA-4 checkpoint immunotherapy with CSF-1/CSF-1R blockade improved anti-tumour immunity and led to the regression of even established primary pancreatic tumours." (PMID 31331034, 2019). "CTLA4 that encodes an immune checkpoint receptor, was found to be transcribed in OSCC-GB tumour tissue by five- to six-fold (adjusted p < 0.05) higher than normal tissue (six-fold higher in discovery cohort; five-fold higher in validation cohort)." (PMID 31796082, 2019). "There is a new viewpoint indicating that anti-CTLA-4 antibodies induce tumor recession by the selective depletion of Tregs in tumors rather than the blocking of B7-CTLA-4 interaction in lymphoid organs." (PMID 31708918, 2019). "This clinical trial included on-treatment biopsies at the time of ablation, which revealed that CD8+ T cell infiltration at six weeks after initiation of anti-CTLA-4 correlated with tumor response." (PMID 31627733, 2019). "Presently, research indicates CTLA4 blockades act within lymph nodes, whereas PD-1/PD-L1 blockades act primarily in tumor tissues." (PMID 31014381, 2019).
tumor (continued). "Anti‐CTLA4 antibody binds with the tumour cell‐intrinsic CTLA4 and activates the EGFR pathway to induce PD‐L1 expression." (PMID 30378264, 2019). "Immunotherapy of cancers with checkpoint inhibitor blocking antibodies, such as anti-PD-L1 or anti-CTLA4, is only effective for about 1⁄4 of patients with preexisting tumor-infiltrating effector T cells." (PMID 31161238, 2019). "CTLA-4 increases the activation threshold of T cells, reducing immune responses to weak antigens such as self- and tumor antigens." (PMID 31248118, 2019). "A proposed secondary mechanism of CTLA-4 mAbs is that of Treg depletion within the tumor microenvironment (TME), as some studies have shown that decrease in Tregs with anti-CTLA-4 therapy." (PMID 31640266, 2019). "PD1 and CTLA4 are T cell-expressed immunomodulatory receptors, whereas PD-L1 (to PD1) and CD80 (to CTLA4) are binding partners present on tumor cells and macrophages, and dendritic cells, respectively." (PMID 30474694, 2019). "It is important to highlight that the tumor growth reduced more than 90% when CSF1R blockade was combined with either anti-CTLA-4 or anti-PD-1 compared to the mice treated only with anti-CTLA-4 or anti-PD-1 alone." (PMID 30987642, 2019). "Among the immune checkpoints, PD-1 and CTLA-4 expressed by T cells and PD-L1 expressed by tumor cells have been the most studied." (PMID 30999966, 2019). "The analysis of the expression level of CTLA-4 in tumor cells and interstitial lymphocytes can provide a basis for the selection of patients with the most effective immunotherapy." (PMID 31485274, 2019). "In 1996, James Allison and colleagues first reported that treating tumor-bearing immune competent mice with anti-CTLA-4 antagonist mAb resulted in tumor rejection, suggesting that removing T cell co-inhibitory signal was an effective approach to treat cancer." (PMID 31186046, 2019). "To prioritize investigation of immune checkpoint pathways to target in select PA patients, we first examined expression of ligands for PD1 and CTLA4 in PA tumor and immune cells." (PMID 31427603, 2019). "Cytotoxic T lymphocyte antigen‐4 (CTLA‐4) binds its ligand, B7, to produce inhibitory signals, inhibit T cell activation, and protect tumor cells from T cell attack." (PMID 31365790, 2019). "We next examined the effects of anti‐CTLA4 and anti‐PD‐1 treatment on xenograft tumour growth in nude mice." (PMID 30378264, 2019). "Immune checkpoint inhibitors (ICI) targeting cytotoxic T-lymphocyte-associated protein 4 (CTLA-4) and programmed cell dealth-1/program cell death ligand-1 (PD-1/PDL-1) proteins are able to augment host anti-tumor immune response." (PMID 31367835, 2019). "In this case, the tumor was refractory to chemotherapy; the treatment, therefore, included radiotherapy to the metastatic lesions in the liver along with anti-CTLA-4 administration." (PMID 31455032, 2019). "CTLA-4 immunoexpression in tumor cells has been quite controversial in literature, as has been choice of antibody for this protein, despite some reports with positive findings." (PMID 31614500, 2019). "The importance of this finding is that the CTLA4 protein plays a key role in activating the anti-tumour response against cancer cells." (PMID 31174203, 2019). "ATOR-1015 and the anti-CTLA-4 antibody reduced tumor growth, prolonged survival and cured tumor-bearing mice (complete responders: 1/10 for vehicle; 2/10 for anti-OX40; 6/10 for anti-CTLA-4; 7/10 for ATOR-1015)." (PMID 30975201, 2019). "We showed that the proportion of CD4+CD25+ Tregs in lymphocytes increased significantly after co-culture, and Foxp3, NRP1 and CTLA-4 expression on the surface of the cells were upregulated, indicating that the tumor cells stimulated T cell immune responses." (PMID 31417646, 2019). "The majority of mice treated with the combination of α-PD-1 and α-CTLA-4 exhibited tumor free survival through day 80 of follow up, while all of the mice in the control untreated group exhibited high tumor burden." (PMID 31533840, 2019).
tumor (continued). "al observed that upon early intervention with both PD-1 and CTLA4 blocking antibodies, tumor burdens in their EBV-infected cord blood reconstituted huNSG model were diminished." (PMID 31145756, 2019). "Anti-PD-1 and anti-CTLA-4 treatments both induce the expansion of specific subsets of tumor-infiltrating exhausted-like T cells, and anti-CTLA-4 additionally engages ICOS+ Th1-like CD4 T cells." (PMID 31182061, 2019). "When combining with CTLA‐4 checkpoint inhibitors, they showed strong immune response and memory effect for various types of tumor models." (PMID 30937265, 2019). "When combined with anti-PD1 and anti-CTLA4, ionizing radiation eradicated tumor in a murine subcutaneous PDAC model." (PMID 30796212, 2019). "Collectively, these results indicate that combined anti-PD-1 and anti-CTLA-4 therapy produces a superior, more effective anti-tumor immune response compared to antibody monotherapy in HepFrag mice." (PMID 31291357, 2019). "Since tumour tissues are the main site of the immune responses, activated T cells expressing PD-1 and CTLA-4 are trafficked into tumour tissues." (PMID 31300681, 2019). "In combination therapy, the upregulation of T-cell production by CTLA-4 blockade in TDLNs is observed, and the effect on tumour size is moderately enhanced, compared to the anti-PD-L1 monotherapy." (PMID 31218069, 2019). "In this model, CSF-1/CSF-1R targeting resulted in increased expression of immune checkpoint molecule on tumour cells, including PD-L1 and CTLA-4, thus resulting in only modest increase of CD8+ T cell cytotoxicity." (PMID 31331034, 2019). "These include the CTLA-4, PD-1, and PD-L1 inhibitors, which restore anti-tumor immune responses, leading to a longer survival in a significant proportion of treated patients." (PMID 30975211, 2019). "In vivo tumor tracer uptake correlated with in vitro CTLA-4 expression levels of these tumor cells, with the highest uptake in the A549 cell line 48 h post infusion." (PMID 31696402, 2019). "In immune cells associated with the tumor and the TME, CTLA-4 and PD-1 are up-regulated, leading to an immune tolerance toward cancer." (PMID 31226866, 2019). "In theory, anti-PD-1 (α-PD-1) plus anti-CTLA-4 (α-CTLA-4) treatment simultaneously block two inhibitory signaling pathways of anti-tumor immune response." (PMID 31673481, 2019). "A tumor-specific increase of the CD4+ T-cell response seems more likely to be achieved by CTLA4-blockade than by targeting PD-1, arguing for a combination of PD-L1 and CTLA-4 blockade to reinvigorate the tumor-specific CD4+ T-cell response." (PMID 31481117, 2019). "The anti-tumor efficacy dependent on the Fc-mediated effector functions has also been demonstrated for CTLA-4, TIGIT and VISTA." (PMID 31554169, 2019). "Development of immune checkpoint inhibitors, such as anti-CTLA-4, anti-PD-1 and anti-PD-L1, bypass the immune checkpoint, with the aim of rescuing and enhancing the function of anti-tumor T cells." (PMID 31430935, 2019). "While MSI-H CRCs have more tumor-infiltrating lymphocytes, scientists also found MSI-H tumor microenvironment strongly expressed several checkpoint ligands including PD-1 and CTLA-4." (PMID 31639018, 2019). "Ablation of IL-17RA in the mouse sporadic tumor model resulted in elevated expression of CTLA-4, a cell surface protein that is constitutively expressed in Tregs and mediates part of their immune suppressive function." (PMID 31775909, 2019). "The effector/memory Tregs play a key role in the loss of tumor immunity, even in the presence of cytotoxic CD8+ T cells, and they have greater effector functions and higher CTLA-4 expression in preclinical studies." (PMID 31395100, 2019). "TLR9 injected tumors on the right flank largely resolve; however, resolution of the left flank tumor is only pronounced in combination with CTLA-4 blockade." (PMID 31771649, 2019).
tumor (continued). "We found increased survival of Tmem176b−/− compared with WT tumor-bearing mice following treatment with anti-CTLA-4 monoclonal antibody (mAb)." (PMID 31085177, 2019). "PD-1 and CTLA-4 are the two most actively investigated checkpoint receptors, which play a role in different stages of anti-tumor immune response." (PMID 31244654, 2019). "The pH-sensitive anti-CTLA-4 antibodies described herein not only exhibit better Treg depletion in the tumor but also avoid irAE by preserving CTLA-4 levels to prevent irAE." (PMID 31267017, 2019). "Checkpoint inhibitors, for example, have been developed to target and block the immune checkpoint proteins CTLA-4, PD-1 and PD-L1, which are upregulated on tumour cells and immune cells and restrict the immune system from attacking the tumour." (PMID 31527531, 2019). "Analyzing the tumor immune infiltrate at treatment day 10 revealed a significant increase in CD45+ cells after both anti-CTLA-4 monotherapy and combination therapy with anti-PD-1 antibody." (PMID 31291357, 2019). "A mouse model of CT26 tumour bearing BALB/c mice was used to examine the expression of CTLA-4 on these tumours." (PMID 31656546, 2019). "T-cell immunoglobulin mucin-3 (Tim-3) and cytotoxic T-lymphocyte-associated protein 4 (CTLA-4) are two important co-inhibitory molecules that regulating CD8+ T cells responses during infection and tumor." (PMID 31138782, 2019). "Pioneering work from Jim Allison and co-workers in the mid-1990s showed that antibodies blocking CTLA-4 were able to enhance the anti-tumor immune response in mice, resulting in complete tumor rejection and long-lasting immunity." (PMID 31060225, 2019). "Several mechanisms are responsible of HIF-1 induced tumor growth among which the resistance to T cell–mediated killing by increasing the expression of programmed death–ligand 1 (PD-L1) on tumor cells and the increased expression of CTLA-4 on CD8+ T cells." (PMID 31903166, 2019). "This was expected due to the success of checkpoint inhibitor mAbs such as anti-CTLA-4 and anti-PD-1 alone or in combination in restoring T cell responses and control of tumor growth." (PMID 31455818, 2019). "The combination of α-PD-1 and α-CTLA-4 can suppress tumor development by T cell infiltration into tumors and the induction of polyfunctional effector tumor infiltrating lymphocytes (TIL), probably CD4+ and CD8+ T cells." (PMID 30941374, 2019). "The immunosuppressive action by anti-PD-1 works in the effector phase of the interaction between T lymphocytes and tumor cells, and the blockade of this agent seems to be more effective towards T-cell activation than CTLA-4 blockade." (PMID 31762821, 2019). "IDO was responsible for mediating the adaptive resistance of tumours to PD-1/PD-L1 or CTLA-4 checkpoint blockades." (PMID 30777100, 2019). "In another study, the authors showed that antibody-mediated CTLA-4 blockade increases tumor immunity in some patients who were previously vaccinated with GVAX." (PMID 30923527, 2019). "Immune checkpoint blockade antibodies neutralize important, but specific, immune-regulatory interactions such as PD-1/PD-L1 and CTLA-4 to improve the anti-tumor immune response." (PMID 31379850, 2019). "Evidence for this was provided by i.t. delivery of CTLA-4 blocking antibodies in a mouse model, showing equivalent tumor control to systemic administration with reduced side effects." (PMID 30944963, 2019). "In the tumor immunotherapy setting, CTLA-4-targeting mAbs support the activation and proliferation of effector T cells, resulting in broad activation of immune responses against tumor cells." (PMID 30729114, 2019). "CTLA-4 is expressed on T-cell surfaces and interacts with tumor antigen (Ag) presenting cells (APCs) to suppress the activation of naïve T-cells in lymph nodes (LNs)." (PMID 31754400, 2019). "These two molecules strongly correlated each other and are known to be overexpressed when tumor shows responses to immunotherapy using anti-CTLA-4 or PD-L1 inhibitors." (PMID 31511581, 2019).